RNU6-634P (RNA, U6 small nuclear 634, pseudogene)
Gene: Small nuclear RNA gene on chromosome 2 (55,499,950 to 55,500,055, forward strand). Ensembl gene ENSG00000239189.
Homologues: Orthologues: macaque U6 (81% identical), mouse Gm25599 (61% identical). Paralogues in human: RNU6-1081P (75% identical), RNU6-80P (75% identical), RNU6-144P (75% identical), RNU6-310P (75% identical), RNU6-333P (75% identical), RNU6-35P (75% identical), RNU6-684P (75% identical), RNU6-753P (75% identical), RNU6-1024P (74% identical), RNU6-1131P (74% identical), RNU6-1316P (74% identical), RNU6-20P (74% identical), and 1284 more.